TRIM4 (tripartite motif containing 4)
Description:
E3 ubiquitin-protein ligase. Mediates 'Lys-63'-linked polyubiquitination of the innate immune receptor RIGI, this linkage doesn't lead to proteasomal degradation but seems to enhance IFN induction.
Synonyms: RNF87
Tractability: Antibody: its Gene Ontology location is reachable by antibodies, with high confidence. PROTAC: ubiquitination databases record sites on it; its protein half-life has been measured.
Target class: Enzyme; Transferase
Gene: Protein-coding gene on chromosome 7 (99,876,958 to 99,919,601, reverse strand). Ensembl gene ENSG00000146833.
Subcellular location: Cytoplasm
Subcellular location (Human Protein Atlas): Cytosol; Plasma membrane
Pathways (Reactome):
Immune System: Antigen processing: Ubiquitination & Proteasome degradation; DDX58/IFIH1-mediated induction of interferon-alpha/beta; NF-kB activation through FADD/RIP-1 pathway mediated by caspase-8 and -10; Negative regulators of DDX58/IFIH1 signaling; TRAF3-dependent IRF activation pathway; TRAF6 mediated IRF7 activation; TRAF6 mediated NF-kB activation
Disease: SARS-CoV-2 activates/modulates innate and adaptive immune responses
Metabolism of proteins: Ovarian tumor domain proteases
Gene Ontology:
Molecular function: identical protein binding; ubiquitin-protein transferase activity; ubiquitin protein ligase activity; zinc ion binding
Biological process: innate immune response; regulation of gene expression; protein ubiquitination
Cellular component: cytoplasm; cytosol
Genetic constraint (gnomAD): Loss-of-function variants: 28 observed, 28.38 expected, observed/expected ratio (o/e) 0.99, 90% interval 0.73 to 1.35. The upper end of that interval is the gene's LOEUF score, 1.35, which puts it in group 5 of 6, group 1 being the genes least tolerant of losing a copy. Missense variants: 551 observed, 570.56 expected, observed/expected ratio (o/e) 0.97, 90% interval 0.9 to 1.04. Synonymous variants: 224 observed, 217.84 expected, observed/expected ratio (o/e) 1.03, 90% interval 0.92 to 1.15.
Homologues: Orthologues: chimpanzee TRIM4 (99% identical), macaque TRIM4 (96% identical), dog TRIM4 (78% identical), rabbit TRIM4 (76% identical), pig TRIM4 (70% identical). Paralogues in human: TRIM58 (37% identical), TRIM11 (36% identical), TRIM21 (35% identical), TRIM17 (35% identical), TRIM39 (34% identical), TRIM27 (34% identical), TRIM41 (31% identical), TRIM7 (31% identical), TRIM26 (31% identical), TRIML1 (31% identical), TRIM10 (30% identical), TRIM69 (28% identical), and 68 more.
Diseases named in the same sentence as TRIM4 in open-access papers:
TRIM4 is named in the same sentence as 24 diseases in open-access papers, as found by Europe PMC text mining. Sharing a sentence is not in itself a finding about the gene and the disease. The quoted sentences say what the papers report.
viral infection (7 papers, 2019 to 2025). "The impact of TRIM4 on virus infection was further determined in the cells with TRIM4 overexpression." (PMID 41170971, 2025). "It is reported that human TRIM4 participates in the antiviral reaction by targeting RIG-I in response to viral infection via an indirect interaction, and maintains the function of TRIM4 together." (PMID 35637527, 2022). "The changes in TRIM4 at different time points of viral infection were further analyzed." (PMID 35242838, 2022). "MEX3C, TRIM4 and TRIM25 are the most important E3 ligases for positive regulation of RIG-I activity in response to viral infection, whereas RNF122 and RNF125 have been described to mediate the ubiquitin-dependent degradation of this cytosolic innate immune receptor." (PMID 32019099, 2020).
breast carcinoma (3 papers, 2022 to 2025). "Herein, we provide evidence that TRIM4 is downregulated in TAM‐resistant breast cancer cells, and that the loss of TRIM4 expression is associated with hormone receptor‐independent phenotypes, including TAM resistance and triple‐negative breast cancer (TNBC)." (PMID 35843886, 2022). "Next, the associations between SET or TRIM4 expression and breast cancer patient clinicopathological characteristics were assessed." (PMID 35843886, 2022). "Here, it is found that TRIM4 is downregulated in tamoxifen (TAM)‐resistant breast cancer cells, while the loss of TRIM4 is associated with an unfavorable prognosis." (PMID 35843886, 2022). "Together, these data suggested that TRIM4 loss was closely tied to breast cancer cell proliferation, metastasis, and TAM resistance." (PMID 35843886, 2022). "TRIM4 is shown to enhance ERα activity in breast cancer cells by targeting SET proteins for ubiquitination-mediated degradation." (PMID 39851497, 2025). "In the absence of TRIM4, ER+ breast cancer cells become tamoxifen resistant, and TRIM4 was found to be downregulated in ER+ breast cancer, suggesting a tumor suppressor role for this ligase." (PMID 39851497, 2025). "Our data also underscored the critical role of TRIM4 in breast cancer stem cells based on the observed proportions of CD44+/CD24− cells." (PMID 35843886, 2022). "In vitro and in vivo experiments confirm that TRIM4 increased ER‐α expression and the sensitivity of breast cancer cells to TAM." (PMID 35843886, 2022). "Together, these results confirmed the ability of TRIM4 to suppress breast cancer development and resistance to TAM treatment." (PMID 35843886, 2022). "Univariate and multivariate Cox proportional hazards regression analyses identified only TRIM4 expression as an independent predictor of ER‐α positive breast cancer patient OS and RFS." (PMID 35843886, 2022). "Next, we explored the functional role of TRIM4 as a regulator of ER‐α‐positive breast cancer TAM resistance in a murine xenograft model system." (PMID 35843886, 2022). "Consistently higher levels of TRIM4 protein expression were evident in luminal breast cancer cell lines as compared to TNBC cell lines." (PMID 35843886, 2022). "Together, these results reveal a novel mechanism controlling SET degradation and ER‐α action in breast cancer cells and suggest that TRIM4 is a promising target for efforts to increase breast cancer cell sensitivity to endocrine therapy." (PMID 35843886, 2022). "Taken together, the data highlights a previously undiscovered mechanism and suggest that TRIM4 is a valuable biomarker that can be analyzed to predict response to endocrine therapy in breast cancer patients." (PMID 35843886, 2022). "Together, these findings thus suggested that TRIM4 may be a prognostic biomarker in breast cancer patients, particularly in ER‐α‐positive patients undergoing TAM treatment or other endocrine therapies." (PMID 35843886, 2022). "Together, these results suggest that decreased TRIM4 expression is linked to TAM resistance and poor prognostic outcomes for ER‐α positive breast cancer patients undergoing adjuvant TAM therapy, in line with our results from in vitro studies using TAM‐resistant breast cancer cell lines." (PMID 35843886, 2022). "We further sought to determine whether the TRIM4‐mediated regulation of ER‐α expression also altered ER‐α‐dependent transcription in breast cancer cells." (PMID 35843886, 2022). "Moreover, univariate and multivariate Cox proportional hazards regression analyses confirm that TRIM4 expression is an independent predictor of overall survival and recurrence‐free survival outcomes in patients with ER‐α positive breast cancer." (PMID 35843886, 2022).
breast carcinoma (continued). "To further establish the clinical relevance of TRIM4 as a modulator of TAM sensitivity in breast cancer patients, we next prepared organoids derived from ER‐α‐positive patients which were then infected using TRIM4‐expressing or control retroviruses and plated in organoid culture media and Matrigel." (PMID 35843886, 2022). "Furthermore, knocking down SET expression resulted in TRIM4 dysfunction in breast cancer cells." (PMID 35843886, 2022). "We next assessed whether SET is involved in TRIM4‐mediated TAM sensitivity in breast cancer." (PMID 35843886, 2022). "As the expression of TRIM4 inhibited the phosphorylation of PI3K family proteins, we wanted to further demonstrate the role of the PI3K signaling pathway in TRIM4‐mediated TAM sensitivity and breast cancer cell proliferation." (PMID 35843886, 2022). "In line with gene expression array results, TRIM4 knockdown resulted in decreases in ER‐α and PR expression in the MCF7 and T47D luminal breast cancer cell lines." (PMID 35843886, 2022). "A loss of hormone receptor expression is one of the primary drivers of resistance to antihormonal therapy in breast cancer patients.[3d] An analysis of available TCGA data indicated that TRIM4 expression was closely related to luminal subtypes of breast cancer but not to TNBC." (PMID 35843886, 2022). "We further conducted an IHC analysis of the protein levels of ER‐α and TRIM4 in primary human breast tumor samples collected at Qilu hospital, revealing markedly lower levels of intratumoral expression in patients with TNBC as compared to patients with luminal‐type breast cancer." (PMID 35843886, 2022).
COVID-19 (3 papers, 2021 to 2024). A disease caused by infection with severe acute respiratory syndrome coronavirus 2. "It identified viral protein adjacency to specific host proteins whose regulatory variants are linked to COVID-19 severity, including the TRIM4 interferon signaling regulator which was found proximal to the SARS-CoV-2 M protein." (PMID 33655243, 2021). "Integration of GWAS data in COVID-19 identified SNPs associated with natural variation in the expression of specific genes, including the viral M protein-proximal TRIM4 activator of type I interferon, that may contribute to disease susceptibility differences in the human population." (PMID 33655243, 2021).
hepatocellular carcinoma (3 papers, 2020 to 2022). A malignant tumor that arises from hepatocytes. "WSB1, TRIM4, and RNF144b are associated with multiple cancers including neuroblastoma, chordoma and hepatocellular carcinoma." (PMID 34603387, 2021). "However, the relationship between TRIM4 and human malignancies, including hepatocellular carcinoma (HCC), is unclear." (PMID 32368282, 2020).
colon cancer (2 papers, 2021 to 2025). "Here, we identified the binding relationship between GSPT1 protein and E3 ubiquitin protein ligase (TRIM4) in colon cancer cells." (PMID 33819920, 2021).
Infertility (2 papers, 2024 to 2025). "Although there was evidence for distinct genetic architectures of infertility and reproductive hormones, we showed that individual genes containing rare protein-coding variants associated with testosterone (GPC2, CYP3A43 and TRIM4) were also associated with higher risk of infertility in the UKBB." (PMID 40229599, 2025). "Although there was evidence for distinct genetic architectures of infertility and reproductive hormones, we showed that individual genes containing rare protein-coding variants associated with testosterone (GPC2, CYP3A43, TRIM4) were also associated with higher risk of infertility in the UK Biobank." (PMID 38562841, 2024).
lung carcinoma (2 papers, 2020 to 2023). "We identify ten cancer risk variants including five pleiotropic associations (e.g., rs2076295 at DSP on 6p24 associated with lung cancer and rs2525548 at TRIM4 on 7q22 nominally associated with six cancers)." (PMID 37340002, 2023). "Similarly, the BRAF gene has been found translocated with TRIM4 in lung cancer and TRIM24 in both melanoma and lung cancer and the FGFR1 gene is translocated with TRIM24 in myeloproliferative syndrome." (PMID 32226386, 2020).
colorectal cancer (1 paper, 2020). A primary or metastatic malignant neoplasm that affects the colon or rectum. "These previous studies reported that the expression of TRIM4 and PYGL in colon transverse tissue was associated with colorectal cancer risk, while PTPN2 expression in colon transverse tissue modified the association of diabetes with colorectal cancer risk." (PMID 33142733, 2020).
Huntington disease (1 paper, 2022). Huntington disease (HD) is a rare neurodegenerative disorder of the central nervous system characterized by unwanted choreatic movements, behavioral and psychiatric disturbances and dementia. "Upregulation of MEG3, TRIM4, and TCEAL5 were reported in different models of Huntington’s disease with an intracellular aggregation of mutant HTT, suggesting a link between PSEN1 ΔE9 and mutant HTT-induced transcriptomic changes." (PMID 36552881, 2022).
liver cancer (1 paper, 2020). An epithelial or non-epithelial malignant neoplasm that arises from the liver. "We found that the TRIM4 expression was much lower in HCC tissues than in peritumoural tissues and was significantly associated with vascular invasion, tumour capsule and Hong Kong Liver Cancer (HKLC) stage." (PMID 32368282, 2020).
viral hepatitis (1 paper, 2020). An acute or chronic inflammation of the liver parenchyma caused by viruses. "DNA hypomethylation of DCAF4L2, CKLF and UBE2C was observed in both NASH-related and viral hepatitis-related HCCs, whereas that of TRIM4, PRC1 and TUBA1B occurred in a NASH-related HCC-specific manner." (PMID 32685988, 2020).
tumor (10 papers, 2020 to 2025). "In line with our in vitro results, TRIM4 loss in MCF7 cells was associated with increases in tumor volume relative to controls, while TAM treatment further exaggerated this difference and resulted in a decrease in tumor volume." (PMID 35843886, 2022). "Our findings indicate that knockdown of TRIM4 reduces the anti-tumor effects of Aurovertin B (AB), highlighting TRIM4's importance in TNBC treatment." (PMID 39629122, 2024). "Our data indicated that MLN4924 significantly inhibited AB's anti-tumor effects both in vitro and in vivo, underscoring the importance of the ubiquitination pathway mediated by TRIM4 and NEDD8 neddylation in TNBC progression." (PMID 39629122, 2024). "Univariate analyse revealed that TRIM4 expression, tumour diameter, and vascular invasion were the factors that significantly influenced the OS of HCC patients." (PMID 32368282, 2020). "On the other hand, lower expression of the TRIM4 gene was significantly correlated with poorer tumor differentiation (P = 0.029)." (PMID 32685988, 2020). "Significant differences in TRIM4 staining patterns were generally observed between tumour-adjacent tissues and primary HCC tissues." (PMID 32368282, 2020). "Univariate analysis revealed that TRIM4 expression, tumour diameter, vascular invasion and tumour capsule were predictive factors for intrahepatic recurrence." (PMID 32368282, 2020). "Multivariate analysis revealed that TRIM4 expression (hazard ratio, 0.566; 95% CI, 0.345-0.930; p=0.025), tumour diameter (hazard ratio, 1.804; 95% CI, 1.131-2.876; p=0.013) and vascular invasion (hazard ratio, 1.802; 95% CI, 1.115-2.912; p=0.016) were independent predictive factors for RFS." (PMID 32368282, 2020). "Notably, FAM118A showed RI events, and TRIM4 showed SE events in tumor tissues." (PMID 41219359, 2025). "Lower TRIM4 and higher SET expression levels, respectively, were related to larger tumor size and lymph node metastasis, whereas they were unrelated to age, histological grade, HER‐2, PGR, or Ki‐67 expression." (PMID 35843886, 2022). "The differential expression of TRIM4 makes cells sensitive to H2O2-induced death, which is common in tumor cell lines." (PMID 36466711, 2022). "Our study revealed that TRIM4 expression levels in HCC tissues were negatively associated with vascular invasion and the absence of a tumour capsule, indicating that TRIM4 may be a potential prognostic marker for HCC." (PMID 32368282, 2020).
cancer (5 papers, 2019 to 2025). A tumor composed of atypical neoplastic, often pleomorphic cells that invade other tissues. "We performed colocalization analysis with the eQTL data; variation in TRIM4 gene expression across 11 cancer-related tissues was potentially responsible for the GWAS locus (SS P-value: 1.4 × 10−5−5.4 × 10−5, suggested threshold after multiple testing correction <0.002)." (PMID 37340002, 2023). "Interestingly, TRIM4 expression was initially increased during the establishment of cancer, and thereafter decreased during the process of dedifferentiation from well to poorly differentiated HCC." (PMID 32685988, 2020). "While TRIM4 has not previously been implicated in cancer risk, the strong homology across gene members of this family and their implications in cancer and immunity make this gene an interesting candidate." (PMID 30820706, 2019). "On the other hand, five pleiotropic loci were detected in the all-cancer meta-analysis (e.g., IGF2BP2 on 3q27, PRMT6 on 1p13, and TRIM4 on 7q22)." (PMID 37340002, 2023). "Colon Transverse PrediXcan analyses were repeated for TRIM4 and PYGL in the discovery dataset stratifying cases by proximal (n = 4454 cases), distal (n = 3580 cases), and rectal (n = 2936 cases) cancer sites." (PMID 30820706, 2019).
infection (5 papers, 2019 to 2025). The state of being infected such as from the introduction of a foreign agent such as serum, vaccine, antigenic substance or organism. "The results showed that the expression of TRIM4 was the highest at 36 h post-infection, which was increased by approximately 7-fold, western blotting results showed that the protein level of TRIM4 increased." (PMID 35242838, 2022). "The EV-A71 2C and VP1 proteins were reduced when TRIM4 was knocked down by two siRNA 3 days before EV-A71 infection." (PMID 31001221, 2019). "Consequently, EMCV infection was enhanced by TRIM4 depletion while it was inhibited by TRIM4 overexpression, and nsp8 greatly promoted viral replication under both conditions." (PMID 37956198, 2023). "To investigate the effect of porcine reproductive and respiratory syndrome virus (PRRSV) infection on TRIM4 expression, we infected MARC145 cells with PRRSV at different multiplicities of infection (MOI)." (PMID 35242838, 2022). "An involvement of TAOK2 and TRIM4 in MDA5 dependent responses is further supported by the lack of IFN production in TAOK2 KO cells after infection with SFV, which is an MDA5 activating virus." (PMID 34853303, 2021).
TRIM4 also shares sentences with these, for which no sentence is quoted: asthma (1 paper); breast tumor (1); chordoma (1); Cirrhosis (1); diabetes (1); glioma (1); Hepatitis (1); neuroblastoma (1); triple-negative breast carcinoma (1); viral pneumonia (1).